BCL2 (BCL2 apoptosis regulator)
Diseases named in the same sentence as BCL2 in open-access papers (continued):
Sharing a sentence is not in itself a finding about the gene and the disease.
leukemia (continued). "CG-806 demonstrated much more pronounced anti-proliferative than pro-apoptotic effects, accompanied by only marginal inhibition of Bcl-2, Bcl-xL, and Mcl-1 as well in most of the tested leukemia cell lines, even upregulated the anti-apoptotic protein Mcl-1 in Ba/F3-FLT3-WT and ITD mutant cells." (PMID 36865133, 2023). "In addition, gossypol, a natural phenolic compound found in cotton plants, has been depicted as inhibiting Bcl-2, Bcl-xL, Bcl-W, and Mcl-1 in various cancers, including prostate cancer, breast cancer, leukemia, and gliobastoma." (PMID 36982637, 2023). "We found that sorafenib upregulated BCL2 expression in leukemia cells, while JAK-STAT3 inhibition decreased the expression of BCL2 induced by sorafenib, suggesting that leukemia cells upregulate the expression of BCL2 through the JAK-STAT3 pathway, leading to resistance to sorafenib." (PMID 37887047, 2023). "Notably, the honokiol-induced CyP-D expression further impaired Bcl-2 and Bcl-xL balance, triggering apoptosis in the resistant leukemia cells." (PMID 36982637, 2023). "S1g-6, an HSP70 inhibitor, plus Bcl-2/Mcl-1/Bcl-xl triple inhibitor S1 or FDA approved Bcl-2 inhibitor ABT-199 showed synergistic effect with S1g-6 in inducing tumor regression by inducing apoptosis in leukemia cells." (PMID 37189349, 2023). "The expression of BCL-2 in leukemia cells was detected by FCM in 23 of the 31 patients." (PMID 36629738, 2023). "For example, overexpression of BCL-2, an X-linked inhibitor of apoptosis protein (XIAP), and myeloid cell leukemia 1 (MCL-1) blocks the intrinsic apoptotic pathway and confers resistance to chemotherapy in leukemia." (PMID 35992795, 2022). "Moreover, the downregulation of Bcl-2 has been shown to increase autophagic apoptosis in human leukemia cells." (PMID 35815056, 2022). "Previous studies have shown that vitexin treatment leads to apoptosis, a reduction in mitochondrial membrane potential and Bcl-2 protein expression and elevated Caspase-3 and Caspase-9 protein expression in human non-small-cell lung cancer A549 cells and human leukemia K-562 cells." (PMID 35281458, 2022). "Importantly, the combination treatment resulted in markedly reduced leukemia loads in all compartments, indicating significant synergistic anti-leukemia activity of co-inhibition of BCL-2 and MCL-1 in vivo." (PMID 35031695, 2022). "Intriguingly, VDT could directly activate the mitochondrial apoptosis pathway in leukemia cells in the presence of antiapoptotic Bcl-2 proteins." (PMID 36347842, 2022). "Therefore, they represent promising anti-cancer therapeutics, and their potential for the treatment of cancer has been highlighted by the clinical success of the selective Bcl-2 inhibitor ABT-199 in the treatment of leukemia." (PMID 35013156, 2022). "BCL-2 has been identified as an antiapoptotic protein and promotes survival of leukemia stem cells." (PMID 35515507, 2022). "Likewise, inhibitors of BCL-2 (venotoclax), which are already used in the treatment of refractory leukemia in adults, provide hope for improving treatment outcomes in children with refractory myeloid leukemia." (PMID 35875115, 2022). "753B PROTAC, which causes BCL-XL/BCL-2 ubiquitination and selective degradation of cells expressing VHL, is an innovative approach to inducing apoptosis activation and eliminating chemotherapy-induced senescent leukemia cells." (PMID 36291779, 2022). "In mouse models of NPM1-mutated/FLT3-ITD AML, venetoclax plus menin inhibitor was superior to the menin inhibitor alone, in eliminating leukemic cells (including leukemia stem/progenitor cells), decreasing Bcl-2 and Bcl-xL levels, and significantly prolonging mice OS." (PMID 36008542, 2022). "Targeting MCL-1 may dysregulate the cellular metabolism and leukemia–stroma interactions and re-sensitize acute myeloid leukemia to BCL-2 inhibition." (PMID 36293442, 2022). "TR exerted cytotoxicity even in leukemia cells overexpressing BCL2/BCL-xL antiapoptotic proteins." (PMID 36294912, 2022).
leukemia (continued). "In summary, we have identified in the IS21 compound a pan ligand for Bcl-2, Bcl-xL and Mcl-1 anti-apoptotic members, which exhibits potent in vitro and in vivo efficacy against human leukemia and melanoma cancer models, offering the potential for further preclinical investigation." (PMID 35265218, 2022). "MCL-1 inhibitors resensitizes AML to BCL-2 inhibition by regulating leukemia cell bioenergetics and carbohydrate metabolism, including the TCA cycle, glycolysis and pentose phosphate pathway and modulating cell adhesion proteins and leukemia-stromal interactions." (PMID 36544784, 2022). "Among other major results, TR presented selective efficacy against leukemia cells compared with peripheral blood mononuclear cells (PBMCs), and its cytotoxicity was observed even against leukemia model cells overexpressing antiapoptotic BCL-2/BCL-xL proteins." (PMID 36294912, 2022). "Translocation of BCL2 onto Ig light chain genes, BCL2 gene amplification, and other mechanisms yielding BCL2 over-expression are, in contrast, rare in FL and rather promote other types of B-cell lymphoma, leukemia, or multiple myeloma." (PMID 36358756, 2022). "In addition, numerous recent studies have reported that CSCs in several types of cancer, such as leukemia, lung cancer, and colon cancer, exhibited overexpression of BCL-2 and BCL-XL that contributed to CSC survival." (PMID 36411463, 2022). "Bcl-2 upregulation in leukemia cells contributes to the resistance of IDA or cytarabine in AML." (PMID 36355485, 2022). "The observation agrees with recent findings of the MYC and BCL2 loci in leukemia cells." (PMID 34880227, 2021). "We found that CDM combined with ASA significantly accelerated cell apoptosis by downregulation of Bcl-2 and activation of caspase-3, indicating that the combination treatment might be a potential strategy for the treatment of leukemia." (PMID 34568314, 2021). "In addition to Myc and Bcl2, other tumor-promoting genes such as Eef2 and Myh10 were upregulated in leukemia cells, whereas tumor suppressors such as Ikzf1, Ikzf2, Arid1b, Arid2, Samhd1, Bach2, and Myo18b were downregulated." (PMID 34907175, 2021). "For us, all these characteristics resulted in little available material to increase the size of the cohort of study, vary concentrations and exposures to the drug or to further into the mechanisms of action and deepen into the role of Bcl-2 inhibition in this leukemia." (PMID 34381700, 2021). "According to the previous literature, we found that TSRP could induce cell apoptosis on HL-60 leukemia cells, which is mainly through Bcl-2 and Fas signaling pathway in protein and mRNA levels." (PMID 33111956, 2021). "Therefore, PROTACs that can degrade both BCL-xL and BCL-2 should have a broader application for the treatment of leukemia and solid tumors than DT2216." (PMID 34824248, 2021). "ALL leukemia cells generally depend on BCL2 for their survival (Moore, Schlis, Sallan, Armstrong, and Letai, 2008), therefore, a slight diminish in BCL2 expression levels, might significantly affect cell survival in these cells." (PMID 34837933, 2021). "These leukemias undergo remission upon repression of BCL2 expression." (PMID 34484175, 2021). "Recent large scale analyses of the common integration sites of two BCL2 transgenic strains infected with Moloney MuLV (MoMuLV) shows a statistically significant bias toward verified drivers of human B lymphoma and leukemia (Pou2f2, Pax5, Ikzf3, Ebf1) in addition to dozens of other candidate loci." (PMID 34484175, 2021).
leukemia (continued). "Therefore, a PROTAC, such as 753b, that can degrade both BCL-xL and BCL-2, should be more effective and have a broader application for the therapy of leukemia and solid tumors than DT2216." (PMID 34824248, 2021). "Importantly, there was a partial effect of single-gene knockout of Bcl2 and Sox4 on leukemia initiation and maintenance." (PMID 34310280, 2021). "Understanding the regulation of genes such as MYC and BCL2, and more broadly growth and apoptosis pathways, is key to understanding leukemic behavior and may also inform the ways in which leukemias acquire resistance." (PMID 34088716, 2021). "Similarly, changes in metabolic activity are observed in the treatment of leukemia patients with the oral BCL-2 inhibitor venetoclax combined with demethylating agents." (PMID 34681910, 2021). "We have shown that heptamer-type sgRNAs designed to target the human BCL2 or WT1 mRNA efficiently induce apoptosis in human leukemia cells and that heptamer-type sgRNAs designed to target the human BCL2 or CCND1 mRNA efficiently trigger apoptosis in human myeloma cells." (PMID 33553691, 2021). "Finally, we conducted B-cell lymphoma-2 (BCL-2) homology domain 3 (BH3) profiling to identify BH3 peptides responsible for treatment resistance in MLL-leukaemia." (PMID 33581643, 2021). "Furthermore, agents with known anti-leukemia activity, e.g. steroids, proteasome, and HDAC inhibitors, but also BCL-2 and cIAP antagonists or tyrosine kinase inhibitors also emerged with potent anti-leukemia activity." (PMID 32591499, 2020). "BCL2 was also identified as a target of the miR-17-92 family in leukemia." (PMID 32365562, 2020). "These coumadin hybrids can up-regulate the expression of caspase-3 proteins in HCC cell lines and caspase-3 and caspase-9 proteins in leukemia cell lines, and down-regulate the expression of Bcl-2 and the up-regulation of Bax protein expression levels in HCC and leukemia cell lines." (PMID 33344242, 2020). "Particularly, in leukemia, Bcl-2/Bax ratio is an important determinant of cell survival." (PMID 32922508, 2020). "In leukemia cells Bcl-2 has an antioxidant function as a safeguard of mitochondrial integrity by facilitating glutathione import to the mitochondrial matrix or by directly reducing ROS generation, which results in the protection from mitochondrial uncoupling-induced apoptosis." (PMID 32133293, 2020). "Jacarelhyperol A caused a dose-dependent decrease in the cell viability of different types of leukemia cells, such as K 562, HL-60, and THP-1 by blocking the heterodimerization of Mcl-1 with BCL2-associated X (Bax), and Bcl-xL/Bcl-2 with Bak, with IC50 values from 1.52 to 6.92 μM." (PMID 33375664, 2020). "High PRKCA levels in leukemia cells protect the cells from apoptosis via BCL2 activation." (PMID 33488754, 2020). "Furthermore, Venetoclax, a FDA approved BCL2 inhibitor for leukemia, suppressed proliferation of a human HSC cell line and expression of fibrotic genes." (PMID 32650615, 2020). "In the leukemia model, cancer cell-secreted factors such as VEGF activate ECs in a paracrine fashion to support leukemia expansion by releasing leukemic cell trophogens or by increasing leukemic cell survival through HSP90-mediated induction of Bcl-2 expression and apoptosis inhibition." (PMID 32014047, 2020). "In this study, chlorinated guaianolides 1–8, isolated from plants of the genus Centaurea, were evaluated against the human leukemia cell lines HL-60, U-937, a specific U-937 cell line that overexpresses the anti-apoptotic Bcl-2 protein and the human melanoma cell line SK-MEL-1." (PMID 33371413, 2020). "Notably, it has been shown that Bcl-2 overexpression promotes low ROS-producing quiescent leukemia stem cells." (PMID 32133293, 2020). "Importantly, Venetoclax, a potent BCL2 inhibitor approved for the treatment of leukemia, showed promising anti-fibrotic effects in miR-122 knockout mice." (PMID 32650615, 2020).
leukemia (continued). "Furthermore, we showed that treatment with BCL2 inhibitor Venetoclax can effectively suppress leukemia progression from TKI resistant cells." (PMID 33082322, 2020). "Thus, a strong functional dependence of the leukemia cell on BCL-2 (BAD-HRK priming) is highly indicative for ex vivo anti-ALL activity of VEN." (PMID 31358732, 2019). "Thus, we tested the therapeutic role of Bcl-2 inhibition in the treatment of GC-resistant leukaemia cells." (PMID 31462891, 2019). "Moreover, an adaptation of the same mouse model demonstrated that presence of BCL-XL (anti-apoptotic BCL2 member) accelerates the development of MYC-driven leukemia." (PMID 30941349, 2019). "For example, a recent article showed that statins could sensitize leukemia cells to venetoclax, a BCL-2 inhibitor, in a way that is dependent upon GGPP depletion." (PMID 31570763, 2019). "This assumption is in line with previous studies showing that treatment with N-acetyl cysteine, which exerts antioxidant activity by augmenting cellular thiols, reduces DSBs and facilitates non-homologous end joining repair in bone marrow cells in a murine NRAS/BCL2-related model of leukemia." (PMID 30323311, 2019). "In addition, the extract of S. barbata D. Don by methylene chloride also exhibited significant cytotoxicity against human leukemia U937 cells at the concentrations of 5–15 μg/ml via inducing apoptosis by activating caspases and altering the ratio of Bax/Bcl-2." (PMID 31354479, 2019). "Among these apoptotic regulators, it is worth mentioning that the gene expression of BCL2, an antiapoptotic protein overexpressed in CLL associated to leukemia cell survival and therapy resistance, was significantly downregulated in primary CLL cells after treatment with EC-7072." (PMID 31681329, 2019). "Several in vitro studies showed that XN can induce apoptosis by downregulating Bcl-2 or by acitvation of the caspase cascade and can even inhibit the growth of several cancer types like ovarian, breast, colon, prostate, hepatic, pulmonary cancer, and leukemia." (PMID 30678345, 2019). "Interestingly, the most sensitive leukemia with the lowest EC50 value (PDX1) showed the highest BCL-2 protein expression." (PMID 31358732, 2019). "Clinically, prolonged plasma arginine deprivation may be necessary to clear leukaemia cells overexpressing BCL-2." (PMID 30578463, 2019). "Similarly, cooperativity between XIAP inhibitors and TRAIL resulted in a strong apoptotic response in pancreatic carcinoma or leukemia cells, capable to even overcome a Bcl-2-mediated resistance." (PMID 29927992, 2018). "Consistently, we describe how forskolin in combinatorial treatments markedly enhances the toxicity of the epigenetic agent GSKJ4 in leukemia cells, inducing apoptotic cell death paralleled by a strong reduction of BCL-2 protein levels, via a mechanism dependent on PKA activity." (PMID 30079022, 2018). "However, the expression of apoptosis regulatory gene Bcl2 was decreased in Necdin null leukemia cells compared to wild-type leukemia cells." (PMID 29152105, 2017). "Moreover, leukemia onset was dramatically accelerated when this transgenic line was crossed with another line overexpressing the zebrafish bcl2 gene, indicating synergy between the NOTCH pathway and the BCL2-mediated antiapoptotic pathway." (PMID 28930163, 2017).
leukemia (continued). "Because BCL-2 expression in E2A-PBX1 leukemias is comparable to that in normal pre-B cells, we reasoned that this leukemia subtype may be a useful point of comparison with MLL-AF4 cells." (PMID 27856324, 2017). "Additionally, the treatment of leukemia cells with ZINC69391 resulted in mitochondrial membrane function loss and an increase in Bcl-2 phosphorylation in a time dependent manner, both events associated to apoptosis induction." (PMID 29228706, 2017). "Bcl2 has been previously shown to confer TRAIL resistance to leukemia cells." (PMID 27013583, 2016). "This reduced the level of anti-apoptotic bcl-2 protein expression in human leukaemia cells." (PMID 27576529, 2016). "BCL2, an inhibitor of the mitochondrial apoptosis pathway, is the founding member of a large family of BH-domain-containing proteins with activities upstream of caspase activation.BCL2 has emerged as a potential therapeutic target in both leukemia and solid tumors." (PMID 27008505, 2016). "Interestingly, BCL2 was also shown to be essential for the survival effect of RUNX1 in human MLL fusion leukemia." (PMID 26919255, 2016). "E/Rtg mice were bred with Vav-BCL2 transgenic mice to assess whether the antiapoptotic protein BCL2 would cooperate with ETV6/RUNX1 to initiate leukemia." (PMID 26919255, 2016). "We also report that, like other FAO inhibitors, both agents and the related biguanide, Phenformin, increase sensitivity to apoptosis induction by the bcl-2 inhibitor ABT-737 supporting the notion that electron transport antagonizes activation of the intrinsic apoptosis pathway in leukemia cells." (PMID 27283492, 2016). "Differences between the cytotoxic activities of obatoclax and ABT-737 found in the present study may depend on the expression profile of anti-apoptotic Bcl-2 proteins in leukemia cell lines." (PMID 26880588, 2016). "Previous studies have documented synergistic anti-leukemia efficacy of dual BCL-2/XL inhibitor ABT-737 in ALL cells, including xenograft models upon combination with VXL, the regimen used here; this synergy was attributed to the ability of L-ASP to downregulate MCL-1 protein levels." (PMID 26711339, 2015). "Indeed, Bcl-2 overexpression in leukemia types confers resistance to a wide range of antineoplastic drugs and this phenomenon has also been observed in other cancers." (PMID 26688757, 2015). "Although it has not been investigated here, the regulation of Bcl-2 by miR-21 may also participate in sorafenib resistance, as ani-miR-21 was shown to increase autophagy and chemosensitivity of leukemia cells by upregulating Bcl-2 expression." (PMID 26311740, 2015). "Targeting of Bcl-2 was also found in colorectal cancer and leukemia by Zhang and Cimmino." (PMID 25101302, 2014). "Further research will focus on whether Mcl-1 and Bcl-2 could be directly target by miR-29 and miR-29b and how will they work in leukemia cells." (PMID 25006537, 2014). "We could not rule out other mechanisms that Vav1 played in corresponding to the growth and development cancer, as Vav1 might also protect cells from apoptosis by enhancing anti-apoptotic Bcl2 transcription that we reported in leukemia cells." (PMID 24905577, 2014). "Finally, we examined the therapeutic potential of BCL2 inhibition by evaluating the ability of ABT-737 to inhibit growth of primary leukaemia cells in vivo." (PMID 24280866, 2014). "The present results suggest that CAUE is a potent inhibitor of Bcl-2 and may be an effective chemotherapy for leukemia." (PMID 23229564, 2013).